IL10 (interleukin 10)
Diseases named in the same sentence as IL10 in open-access papers (continued):
Sharing a sentence is not in itself a finding about the gene and the disease.
infection (continued). "Significantly high level of IL-10 positively correlated with IgG4 have been observed in infected children born to infected mother, while high level of IFN-γ positively correlated with IgG3 was found in infection free children born to mother free from infection at the time of pregnancy." (PMID 30252839, 2018). "Notably, IL-10 was up-regulated after CH strain infection, but IFN-γ expression did not change significantly." (PMID 29700351, 2018). "Interestingly, the absence of IL-10 during the infection with A54970 strain leads to similar bacterial load in the lungs and no bacterial load in the spleen (data not shown)." (PMID 30518854, 2018). "The expression of IL-10 increased when BECs were incubated with SB at 6 h post infection, whereas in the presence of Akt-IV, no change in IL-10 peptide compared to control was observed, indicating that active Akt (inactive GSK3α/β) was required to induce IL-10 synthesis." (PMID 29434603, 2018). "IL-10 production by siLP Treg of SPF mice did not change in response to infection." (PMID 30349532, 2018). "The anti-inflammatory cytokine, IL-10 was not elicited by both Brucella and ΔGntR infection." (PMID 29435171, 2018). "Serum concentration of IL-10 (limit of detection 17.5 pg/ml) and IL-12p70 (limit of detection 10.7 pg/ml) remained below the detection limit for the assay in more than half of the serum samples throughout the course of infection (data not shown)." (PMID 29403488, 2018). "However, the production of anti-inflammatory IL-10 during infection has not been clearly demonstrated." (PMID 30087675, 2018). "Collectively, these data show that schistosome eggs or their soluble antigens on their own are sufficient to induce IL-10-producing Breg cells in vivo, without the context of natural infection, and that these B cells are bona fide Breg cells that can drive Treg cell development." (PMID 28753651, 2017). "On the other hand, the high levels of pro-inflammatory cytokines detected in the serum of infected IL-10−/− mice at similar time points post infection indicate that the absence of IL-10 allows the recognition of bacteria to generate an inflammatory immune response." (PMID 28824622, 2017). "Analysis of cellular immune responses against P. papatasi saliva in PBMC from individuals naturally exposed to L. major infection, showed low proliferation, absence of IFN-γ production but significant IL-10 levels, which could favor establishment of infection." (PMID 29023574, 2017). "Although transgenic mice overexpressing IL-10 in the macrophage/monocyte compartment exhibit enhanced susceptibility to M. tuberculosis infection, we showed in this study that specific deletion of Il10 in these cells did not affect bacterial growth during infection." (PMID 28584007, 2017). "In a previous work, it was found that an 8-week-long infection of C57BL/6 mice with T. crassiceps induced a suppressive milieu rich in alternatively activated macrophages (AAMs), myeloid-derived suppressor cells (MDSCs), and IL-10, which was able to regulate the EAE development." (PMID 28744067, 2017). "Infection with either Col1.7G2 or Y strain did not change the expression of IL-10." (PMID 29176759, 2017). "In conclusion, this is the first evidence that M2 expression alone, in the absence of an ongoing infection and other viral factors, can support the activated GC B cell phenotype and directly promote PC differentiation and IL10 production from stimulated B cells in vivo." (PMID 28767707, 2017). "Five days post infection with T. spiralis, chitosan appeared to influence the levels of myeloperoxidase (MPO) and cytokines in mice: higher levels of MPO, MCP-1, TNF-α, IL-12p70, IL-6, IL-10 and TGF-β were found in infected mice treated with chitosan compared to those who were not." (PMID 29156562, 2017).
infection (continued). "In addition, our transcriptional profiling identified a functional difference between well-documented cytokines and chemokines between elite controllers and rapid progressors during early infection; there was a significant co-expression of MCP1, TNF and IL10 only in elite controllers." (PMID 28350860, 2017). "Depletion of IL-6 in the early stages of infection resulted in enhanced disease characterized by an influx of IFN-γ secreting virus specific T cells into the lungs and airways, dysregulation of regulatory T cell responses and reduced production of the immune-regulatory cytokines IL-10 and IL-27." (PMID 28953978, 2017). "While indisputably the most dominating cytokine induced by infection in this model system, a diversity of additional expressed and modulating cytokines like IL-6, IL-12, MCP-1, IFN-β, IFN-γ and IL-10 may also contribute to the therapeutic outcome with bacteria." (PMID 28445131, 2017). "However, Tregs only accounted for approximately 10% of the total IL-10+CD4+ T cells in the uninfected mice and slightly more than 15% of the total IL-10+CD4+ T cells in the infected mice, congruous with an infection-dependent increase in IL-10 production by Foxp3+CD4+ T cells." (PMID 28710387, 2017). "Interestingly, the set of data [EPO + hemopexin + total heme] correlated significantly to [TNF-α + IL-10 + IP-10 + MCP-1] during infection, and more specifically for the CM, and NCM groups, but not for MM patients." (PMID 27441662, 2016). "Neither IL-27 nor ICOS played a role in the development of parasite-specific CD4+ YFP+ T cell responses during infection, implying that these pathways specifically modify the induction of IL-10 expression, rather than modifying the initial development of the Th1 response." (PMID 26459508, 2016). "While brain pathology has been well-documented in this model, behavioural assessments have not been performed to confirm that infection had severe effects on general health, neurological reflexes, and baseline behaviours in IL-10−/− mice infected with P. chabaudi." (PMID 27557867, 2016). "We have resolved how CD4+ IFN-γ+ IL-10+ T cells distribute systemically within nonlymphoid tissues during infection to limit inflammation, and we have identified pathways that orchestrate IL-10 production by effector CD4+ IFN-γ+ T cells, potentially at distinct phases of infection." (PMID 26459508, 2016). "In order to assess whether or not early circulating plasma TNF-α/IL-10 ratio may indeed be a novel predictive biomarker for hypersusceptibility to infections, we assessed the AUROC of the various logistic models with TNF-α/IL-10, TBSA, and the various continuous severity scores." (PMID 27761434, 2016). "This suggests that, irrespective of tissue location, the level of IL-10 production by the Th1 cell population may be tightly calibrated during infection." (PMID 26459508, 2016). "Therefore, it is reasonable to postulate a more pervasive mechanism in DENV-ADE infection, which does not rely on the suppression of IFNα/β or increased IL-10/IL-6." (PMID 26923481, 2016). "However, CD4+IFN-γ–yellow fluorescent protein (YFP)+IL-10–GFP− memory T cells rapidly express IL-10 during parasite re-exposure, which leads to enhanced IL-10 production during secondary malaria infection compared with primary infection." (PMID 27630165, 2016). "However, in the absence of IFN-I signaling the amount of IL-10 RNA drops dramatically in DC, whereas the amount of infected DC increases, which is not consistent with direct infection triggering IL-10 production." (PMID 26808628, 2016). "However, a recent cross-sectional study in patients with non-progressive HIV-1 infection showed that concentrations of TGF-β1 and IL-10 are significantly decreased in their plasma, while IL-1β, IL-12p70, and TNF-α are increased, compared to patients with progressive infection." (PMID 27379092, 2016).
infection (continued). "Thus, enhanced expression of IL-10 occurs during the early stages of secondary infection and is not simply a consequence of altered parasite burdens." (PMID 27630165, 2016). "Furthermore, we found that IL-10 was induced to express upon initial PCV2 inoculation in PAMs by activation of NF-κB pathway and PI3K/Akt pathway, and further enhanced in latter phase of infection by activation of ERK and p38 MAPK pathways." (PMID 26883107, 2016). "Thus, it is critical to define the cellular sources of IL-10 in these sensitive nonlymphoid compartments during infection." (PMID 26459508, 2016). "Thus, the enhanced IL-10 response during secondary infection is unlikely to be dominantly or solely controlled by the specific environment the CD4+ T cells are exposed to during rechallenge." (PMID 27630165, 2016). "However, then it would be expected that only infected GFP+ cells would produce IL-10 and that IL-10 levels would directly correlate to a cells level of infection, which is not the case." (PMID 26808628, 2016). "The cloning and sequence analysis of hamster genes related to infection with L. donovani in this animal model was described, revealing a non-polarized immune response profile characterized by an increase in expression of IL-2, IL-12, IFN-ɣ, TNF, IL-10 and TGF-β genes." (PMID 27350537, 2016). "The molecules that depicted significant increases in those mAb treated-mice at 96 h after infection were CXCL1 (KC), CCL2 (MCP-1), CCL3 (MIP-1α), CCL4 (MIP-1β), CXCL2 (MIP-2), CXCL5 (LIX), IL-1α, IL-6, G-CSF, M-CSF, and TNF-α (for all, P < 0.01) and IL-1β, IL-15, IL-10, and LIF (for all, P < 0.05)." (PMID 27642235, 2016). "In contrast, IL-10 level was significantly (p≤ 0.05) down regulated (~ 1.8 fold) in siglec-E knockdown cells compared to ~ 3.9 fold in control cells due to the absence of Sias-siglec interaction during infection." (PMID 27494323, 2016). "Due to this absence of association, we suggest that the necessary equilibrium to control the infection is not present in the VK247, since there is a high inflammatory response and parasite load, without association to the counter-regulatory effect of IL-10 cytokine." (PMID 26943639, 2016). "However, our data does not preclude an IL-10-independent inhibitory function for IL-27 during the later stages of infection." (PMID 27926930, 2016). "Despite the preponderance of IL-10 production during infection, we do not know the tissue distribution of this cytokine or whether it acts in localized areas." (PMID 26991092, 2016). "Hence, a lower infection dose resulted in more KLRG-1-expressing Th1 cells, but although this was exacerbated following all antibody treatment, it did not appear to explain why GITR activation reversed the anti-parasitic effects of IL-10 signaling blockade." (PMID 26872334, 2016). "However, the amount of the anti-inflammatory cytokine IL-10 was significantly higher in CT infected mice compared to non-infected mice at both 4 and 40 h after infection." (PMID 27468286, 2016). "Additionally, there was a trend, though it was not statistically significant, of higher relative levels of expression of IL-10 and CXCL10 mRNAs in the nonlymphoid epithelium and follicle-associated epithelium of cattle that had cleared the infection." (PMID 27147736, 2016). "In the chronic infection at day 98 post-infection, despite the reduction in parasite load, we could not detect any modulation of IFN-gamma, IL-4, TGF-beta and IL-10." (PMID 27716449, 2016). "Increased expression of IL-10 may also be important for species-specific differences between filoviruses, as elevated IL-10 expression was observed later in in vitro infection with BDBV but not EBOV." (PMID 26512687, 2015). "Interleukin 10 was found induced at the later stage of the infection whereas no induction of CD8 or γ IFN could be detected." (PMID 26397117, 2015). "Interleukin 10 transcripts were detected at the late stage of infection whereas no induction of CD8 or γIFN could be detected." (PMID 26397117, 2015).
infection (continued). "Differences in IL-10 levels among infection status groups were not statistically significant." (PMID 25888883, 2015). "Infection did not result in increased IL-10 production by CD4− cells (data not shown)." (PMID 26195548, 2015). "Furthermore, infection failed to induce Foxp3+ Treg cells to produce the suppressive cytokine interleukin 10 (IL-10)." (PMID 26195548, 2015). "Finally, the production of IL-10 in the skin, which derived from a combination of schistosome-specific and commensal microbiota-specific CD4+ T cell responses, contributed towards limiting inflammation and tissue damage following infection." (PMID 25974019, 2015). "In SUDV infection, expression of IL-10 was higher in non-survivors than in survivors." (PMID 26512687, 2015). "In addition, despite the absence of an early protective inflammatory response against F. tularensis infection, the potential role of anti-inflammatory cytokines, such as IL-10, in the progression of infection has not been clearly elucidated." (PMID 26114641, 2015). "We know that IL-10 and TGF-β play similar roles in the inhibitory responses and we can speculate these cytokines might alternate in the balance of pro and anti-inflammatory responses after infection." (PMID 25642946, 2015). "Though the IL-10 levels are high in contacts, they do not progress to infection." (PMID 26359865, 2015). "In addition, IL-10 treatment did not alter barrier permeability as determined by serum albumin levels in recovered BAL fluid 24 h after infection with S. pneumoniae." (PMID 25595646, 2015). "Recovery from infection did not affect the other cytokines, including IL-10, IL-4 and IL-12." (PMID 26637129, 2015). "Infection with C. burnetii did not induce significant production of Il4 or Il10." (PMID 26366725, 2015). "Thus, it is plausible that P. papatasi ADO-induced secretion of SGE IL-10 and PGE2 could induce a tDC profile, thus inhibiting DC function and ultimately contributing to establishment of an infection." (PMID 25849562, 2015). "On the other hand, P. vivax malaria patients presented a significant descrease in the IFN-γ/IL-10 ratio in double-positive (CD45RA+CD45RO+) and memory (CD45RO+) CD8+ T cells when compared to control individuals, indicating a immunomodulatory profile during infection." (PMID 25636730, 2015). "Interestingly, patients who had subsequent infections did not produce TNFα after an LPS challenge, but they did produce IL10 and showed lower levels of pro-inflammatory proteins in plasma than patients with UA." (PMID 24797663, 2014). "Interestingly, this latter effect of type I IFN on DC function was also associated with reduced IL-10 mRNA accumulation in CD8− DCs that lacked type I IFN receptor, potentially linking infection-induced IL-10 production with Th1 regulation once again." (PMID 25352846, 2014). "Additionally, there were no deaths or observed morbidity as a result of IL10 delivery by either AAV vector, even though IL10 is linked to higher infection rates." (PMID 24736312, 2014). "Interestingly, IL-10 (representative of TH2 cytokines) remained relatively constant and still significantly up regulated from the control (p < 0.01) at both 12 and 24 weeks post infection." (PMID 24551602, 2014). "Treatment of filarial infection and consequent cure resulted in significantly decreased frequencies of CD4+ T cells expressing IL-10, IL-19, IL-24 and IL-26 after parasite-antigen stimulation whereas those who continued to harbor infection did not exhibit reduction in these frequencies." (PMID 24699268, 2014). "Because IL-10 has immunosuppressive properties, we questioned whether its generation in the NOS2−/− mice may be an attempt to temper the inflammatory response generated at the site of infection." (PMID 25210773, 2014). "SbS-LD infections also result in production of IL-10 from iTreg cells but not to same extent." (PMID 25032977, 2014).
infection (continued). "Finally, infection with KFDV P9605 also resulted in a significant induction of IL-6, IFN-γ, and MCP-1 in the spleen on day 2, while both KFDV P9605 and AHFV Zaki-1 induced significantly higher levels of IL-10." (PMID 24922308, 2014). "We investigated whether these cytokines have a function similar to IL-10 in individuals with asymptomatic infection and no clinical pathology and those with overt, clinical pathology." (PMID 24699268, 2014). "Both IFN-γ and IL-10 did not significantly change during the whole infection." (PMID 24725777, 2014). "These authors suggest that IL-10 neutralization may be used for boosting immunity against infection without compromising pregnancy outcomes." (PMID 25365504, 2014). "Interference with the action of IL-10 without removal of infection can lead to lethal consequences." (PMID 24942690, 2014). "However, the IL-10 response in these mice waned after infection and was not different from control mice." (PMID 25500571, 2014). "Moreover, activation was not downregulated by IL-10, since no mRNA transcripts were detected for the cytokine in early infection." (PMID 24757289, 2014). "Moreover, to ensure that the observed effect resulted from an absence of IL-10 production, recombinant IL-10 (rIL-10) was added to the IL-10−/− BMDM media during infection." (PMID 23818855, 2013). "However, IL-10 was not secreted by infant B cells harvested up to 20h after LCMV-WE infection (data not shown), suggesting immunoregulatory influences independent of IL-10 producing B cells." (PMID 24376875, 2013). "On day 5 post infection, IL-10 mRNA could no longer be detected in NK and NKT cells, whereas expression persisted in macrophages." (PMID 24244162, 2013). "Notably, differential overexpression of il-10 during lethal infection did not influence global ifn-γ expression, which was comparable in both lethally and nonlethally infected mice on days 3 and 7 p.i.." (PMID 23526993, 2013). "C57BL/6 (B6) mice lacking IL-10 resolve infection with a protective IFN-γ response." (PMID 23675550, 2013). "Additionally, no statistical difference was observed in TNF, IL-10 and IL-4 production in the organ under infection and STAg-pretreatment, despite TNF detection presented a trend to be lower in STAg-pretreated compared to PBS-pretreated mice." (PMID 24086456, 2013). "However, on day 21 after infection, the percentage of IFN-γ-producing CD4+ T cells decreased inside the liver and we found a considerable percentage of CD4+ T cells producing IL-10, including double IFN-γ/IL-10 producers, and some IL-10-producing DCs." (PMID 24312297, 2013). "Furthermore, no immunopathology was apparent in Il21−/− mice over the course of the infection, nor was there a defect in development of IL-10+ CD4+ T cells in chronically infected Il-21−/− mice." (PMID 23667536, 2013). "This is consistent with the observation that the absence of H. hepaticus-induced pathology was reproducibly observed at the MHH facility when C57BL/6 Il10−/− mice of different ages (10–17 weeks at the time of first infection) were infected with H. hepaticus 3B1 (data not shown)." (PMID 23951007, 2013). "However, the ratio of IFN-γ/IL-10 was constant during the infection with predominance of IFN-γ production (data not shown)." (PMID 23577121, 2013). "Presence of the immune-regulatory cytokine IL-10 promotes chronicity of Lymphocytic Choriomeningitis Virus (LCMV) Clone 13 infection, while absence of IL-10/IL-10R signaling early during infection results in viral clearance and higher percentages and numbers of antiviral, cytokine producing T cells." (PMID 24244162, 2013). "Therefore, IL-17 and IL-10 detected in S1 group are considered to be a measure of the exposure without infection while the cytokines measured in S2 group indicates a measure of the infection without disease progression." (PMID 24260295, 2013).